L1CAM (L1 cell adhesion molecule)
Diseases named in the same sentence as L1CAM in open-access papers (continued):
Sharing a sentence is not in itself a finding about the gene and the disease.
tumor (continued). "In the study population of 103 carcinomas, 18 patients showed L1CAM-positive staining in the tumor (17 %)." (PMID 26891628, 2016). "L1CAM recruits of endothelial cells from the expanding tumour, as well as the invasiveness of cancer cells." (PMID 27288147, 2016). "The five tumors, diagnosed as pure UPSC after review of the histological slides, showed L1CAM-expression throughout a major part of the tumor specimens." (PMID 26891628, 2016). "In tumour cells, L1CAM can switch from a cell adhesion to a cell motility promoting role, which is demonstrated by its stimulating effect on invasive growth of tumour cells." (PMID 27028855, 2016). "Since the first record on the analysis of L1CAM expression in human cancer published in 2003, more than sixty studies have explored the role of L1CAM expression in over eighteen types of tumours or malignancies in larger patient groups." (PMID 27833079, 2016). "A fixed-effect or random-effect meta-analytical model was employed to correlate L1CAM expression with different outcome measures in both entire tumours and stratified subgroups." (PMID 27833079, 2016). "Although three cores from different locations in the tumour were included for each patient, chances still are that L1CAM positive areas of the tumour were missed when taking these tissue cores." (PMID 27028855, 2016). "Vimentin expression in the tumour was detected in 29 samples (28.2%) and was correlated to L1CAM expression (Spearman's rho 0.349, P=0.001)." (PMID 27028855, 2016). "This is also illustrated by studies showing high L1CAM expression (sometimes even exclusively), at the invasive border of tumours." (PMID 27028855, 2016). "L1CAM is positivity was particularly present, the cell membranes of the tumor cells, and only weakly present in the cytoplasm of these positive tumor cells." (PMID 26891628, 2016). "To analyse the potential role for L1CAM in tumour cell invasion, we isolated spindle- and cobble-shaped cells from one VSCC which contained both components." (PMID 27028855, 2016). "Paraffin-embedded tumour tissue from two cohorts (N=103 and 245) of primary VSCCs were stained for L1CAM, vimentin and E-cadherin." (PMID 27028855, 2016). "For the following L1CAM, acting during brain development and having an unknowable role in the adult nervous system, the correlation with tumor grade in several other solid human cancers was noted." (PMID 26497896, 2015). "Overexpression of L1CAM has been shown to promote tumor cell proliferation, and accordingly, inhibition of L1CAM expression or function can suppress proliferation." (PMID 25860483, 2015). "Overexpression of L1CAM has been shown to promote tumor cell proliferation, and inhibition of L1CAM expression or function can suppress proliferation." (PMID 25860483, 2015). "We report here that L1CAM is a prototype gene product that is up-regulated in all three tumor entities and confers a bad prognosis to the patients." (PMID 25510351, 2014). "Immunostaining of EMT-associated L1CAM revealed that >60% of the pancreatic duct epithelia in CPs expressed L1CAM (% cells score 2) while in PDACs, approximately 50% of the tumor cells were characterized by a similar expression score." (PMID 24797069, 2014). "L1CAM promotes cell motility, invasion and metastasis formation in various human cancers and can be considered as a driver of tumor progression." (PMID 24497324, 2014). "mAb chCE7 binds with high affinity (KD ≈ 10−10 mol/l) near an RGD sequence in the sixth IgG-like domain of L1CAM, inhibiting tumour cell growth in vitro and in vivo." (PMID 26116117, 2014). "Taken together, these results confirmed massive tumor regression and NF-κb pathway inhibition by L1CAM-siRNA therapy." (PMID 25294816, 2014). "In primary tumor sections areas expressing high amounts of L1CAM had less miR-34a expression than those with low L1CAM levels." (PMID 24497324, 2014).
tumor (continued). "In vivo studies demonstrated that cancer cells overexpressing L1CAM significantly promoted tumor formation, with tumor volumes that were 3–5 times greater than those with low levels of L1CAM expression." (PMID 24660028, 2014). "Previous studies have indicated that L1CAM, a cell surface molecule, promotes tumor cell proliferation." (PMID 24660028, 2014). "iv) The percentage and intensity of FoxP3 (O1–O3) positively correlated with L1CAM expression (P1+P2) in tumor cells." (PMID 24797069, 2014). "Currently, the EMT is a well-accepted mechanism by which the L1CAM leads to a more-aggressive tumor phenotype that was demonstrated in a variety of cancer types." (PMID 25294816, 2014). "Investigations in a variety of tumor types demonstrated that increased expression of L1CAM significantly increases the migration capacity of cancer cells in vitro." (PMID 24660028, 2014). "Metastatic tumor cells often undergo EMT, a process characterized by up-regulation of motility promoting molecules such as the adhesion molecule L1CAM and the loss of epithelial markers such as E-cadherin and cytokeratines." (PMID 24497324, 2014). "High expression of FoxP3, vimentin and L1CAM in PDAC cells as well as a tumor-related localization of macrophages each tended to correlate with higher tumor grade." (PMID 24797069, 2014). "The reduction in PC3-Luc tumor growth by L1CAM siRNA was also confirmed by radiography, which indicated that PC3-Luc tumor-induced osteolytic lesions with destruction of the cortex had dramatically decreased in L1CAM siRNA-treated animals." (PMID 25294816, 2014). "L1CAM protein was detected in 22/92 (23.9%) human non-tumor mucosa samples; all samples expressed L1CAM protein at low levels." (PMID 24422715, 2013). "shRNA targeting of L1CAM expression in glioma cells inhibits tumor growth in vivo and increases the survival time of tumor-bearing animals." (PMID 26317026, 2013). "SSEA-5 and L1CAM warrant further investigation as potentially useful tumor markers for histological evaluation or as markers to monitor the presence of undifferentiated cells in iPSC populations prior to therapeutic use." (PMID 26317026, 2013). "Only in 3 out of 10 paired tumor samples from various EC types a tendency for hypomethylation in L1CAM positive tumor areas was noted." (PMID 23530769, 2013). "L1CAM expression in carcinomas increases the dissemination of tumour cells by enabling cell migration and invasion and promotes the epithelial–mesenchymal transition." (PMID 22544341, 2013). "Recently, the alternative splicing of the cell adhesion molecule L1 (L1CAM) has been found to control the invasive capabilities of tumor cells by regulating MMP-2 and MMP-9 expression and activity." (PMID 24285959, 2013). "Expression of L1CAM correlated with age, tumor location, tumor size, Lauren’s classification, depth of invasion, lymph node and distant metastases, regional lymph node stage and TNM stage (P < 0.05)." (PMID 24422715, 2013). "Our data suggest for the first time that L1CAM expression in HCC was significantly correlated with the advanced tumor progression and was an independent poor prognostic factor for both overall survival and disease-free survival in patients with HCC." (PMID 22888955, 2012). "In contrast to E-cadherin, another type of adhesion molecule, the immunoglobulin superfamily (including NCAM, MCAM, ALCAM and L1CAM, among others), is often highly expressed in metastatic tumour tissues." (PMID 22610942, 2012). "In this study, we first dmonstrate that L1CAM protein and mRNA expression in human HCC tissue was significantly associated with tumor progression and clinicopathologic features." (PMID 22888955, 2012). "L1CAM overexpression is detected in a variety of cancers and is known to promote tumour growth and metastasis." (PMID 21541352, 2011).
tumor (continued). "We demonstrated that the full-length isoform was responsible for the pro-metastatic effect of L1CAM, suggesting an important role of the exons 2 and/or 27 for tumour progression." (PMID 21541352, 2011). "L1CAM was an independent predictor of survival in a multivariate analysis including pT, pN, and pM category, and tumor differentiation grade." (PMID 21985405, 2011). "E-cadherin expression was higher in the tumor center than in the tumor periphery, whereas L1CAM and vimentin were expressed at the tumor-stroma interface." (PMID 21985405, 2011). "The mechanism by which L1CAM leads to a more aggressive tumor phenotype is potentially related to EMT in-vivo and in-vitro." (PMID 21985405, 2011). "In summary, our results show for the first time that L1CAM expression in tumours is regulated by two distinct promoter regions in the L1CAM gene and that Slug is a relevant transcription factor for its regulation." (PMID 20799950, 2010). "But work from experimental systems showed that L1CAM augments tumour growth in NOD/SCID mice, enhances cell motility on extracellular matrix proteins and increases matrigel invasion." (PMID 20799950, 2010). "In immunohistochemical sections, L1CAM expression is often seen at the invasive front where the tumour invades into the surrounding stroma." (PMID 20799950, 2010). "The up-regulation of L1CAM during the EMT process underscores the important role that this molecule plays in tumour progression." (PMID 20799950, 2010). "Recent data have shown that the expression of L1CAM in tumours is upregulated when EMT is induced by TGF-β1 treatment." (PMID 20799950, 2010). "Tumours with low (SK-N-AS) or high (SK-N-BE2c) L1CAM antigen expression were evaluated." (PMID 41366257, 2025). "The L1 cell adhesion molecule (L1CAM) promotes tumor growth and metastasis." (PMID 40302814, 2025). "L1CAM is known to be upregulated in several malignant tumors, where it may contribute to unfavorable outcomes by enhancing tumor cell motility and metastasis." (PMID 40805143, 2025). "To further investigate this, we performed a Neural adhesion assay to evaluate whether L1CAM expression modulates the ability of tumor cells to adhere to nerves, thereby contributing to their invasive behavior." (PMID 40963905, 2025). "However, increasing evidence suggests that L1CAM is also a critical factor in various malignancies, particularly in promoting tumor cell migration, invasion, and neural invasion." (PMID 40963905, 2025). "Therefore, L1CAM expression was analyzed in more than 20,000 tumor tissue samples from 135 different tumor types and subtypes, as well as 76 non-neoplastic tissue categories, using IHC in a tissue microarray (TMA) format in this study." (PMID 41328908, 2025). "Moreover, inhibiting the integrin-binding site on L1CAM (mutating RGD to RGE) or using neutralizing antibodies significantly impaired NF-κB activation and tumor growth." (PMID 40699746, 2025). "SELPLG-deficient L1CAM-CAR T cells were not more effective at limiting tumor growth or improving overall survival than L1CAM-CAR T cells retaining SELPLG expression." (PMID 41394860, 2025). "For example, in pancreatic cancer, the upregulation of L1CAM in tumour-associated endothelial cells (TECs) enhanced IL-6 expression, activating the JAK/STAT3 signaling pathway, which in turn triggered EndMT associated with tumour progression and metastasis." (PMID 40083695, 2025). "Given that infiltrated L1CAM-CAR T cells recognized the antigen at tumor encounter, gene expression levels may be influenced by antigen-dependent CAR T cell activation." (PMID 41394860, 2025).
tumor (continued). "The results highlighted a small number of tumor entities that could be targeted by anti-L1CAM drugs, once these are proved to be sufficiently safe and efficient." (PMID 41328908, 2025). "In small cell lung cancer cell lines, a toxin conjugate with an L1CAM monoclonal antibody successfully inhibited tumor progression, suggesting that this pathway could be druggable." (PMID 40870967, 2025). "The expression of the adhesion molecule L1CAM might aid in the diagnosis of this uncommon neoplasia." (PMID 40289262, 2025). "These patients also showed enrichment in ECM-receptor interactions, integrin–cell surface interactions, focal adhesion, adhesion junctions, laminin interactions, and L1CAM interactions, further supporting their invasive potential and active remodeling of the tumor microenvironment." (PMID 41425595, 2025). "In 10 of 14 tested samples, L1CAM was positive in all or > 50% of the tumour cells." (PMID 40289262, 2025). "We focused on a protein called L1CAM, which is found on the surface of some tumor cells." (PMID 40805143, 2025). "This limitation may have underestimated L1CAM-CAR T cell migratory capacity in a human tumor, as well as their true therapeutic potential and efficacy in humans." (PMID 41394860, 2025). "In the same study, L1CAM was associated with advanced stage, nodal involvement, high tumour grade, non-endometrioid histology, lymphovascular space invasion and distant recurrences." (PMID 41561510, 2025). "Untransduced T cells were able to migrate into the tumor model (mean=22,334 cells, range=20,203-23,004 cells), but their numbers corresponded to only about 10% of the CD28-costimulated and 25% of the 4-1BB–costimulated L1CAM-CAR T cells that infiltrated the 3D tumor model." (PMID 41394860, 2025). "Immunohistochemical analysis of 865 tumor samples from the PORTEC‐1 and PORTEC‐2 trials showed a significant increase in the risk of distant recurrence and pelvic lymph node recurrence with high L1CAM expression." (PMID 39996416, 2025). "Notably, cyclin-dependent kinase inhibitor 2A (CDKN2A) and L1 cell adhesion molecule (L1CAM) hypermethylation correlates with tumor progression and invasiveness." (PMID 40557320, 2025). "However, in brain metastases, this mechanism is regulated by two adhesion proteins expressed by tumor cells: L1CAM and β1 integrin." (PMID 38255995, 2024). "Taken together, last decades' radiopharmaceuticals have been primarily targeting tumor cell membrane proteins (B7-H3, CXCR4, FRα, HER2, integrin αVβ3, L1CAM, mesothelin, MISRII and NaPi2b) besides the (intra-)nuclear target PARP-1 and the FAP-associated tumor microenvironment." (PMID 39431018, 2024). "Moreover, L1CAM mRNA expression is significantly higher at the invasive front compared to the center of the tumor, indicating a supportive role of L1CAM in CRC dissemination." (PMID 37610689, 2024). "Additionally, L1CAM is considered a marker for tumor stem cells and is believed to enhance their resistance." (PMID 39598347, 2024). "Finally, L1CAM positivity was significantly reduced in the tumor tissues after 6TdG treatment consistent with in vitro experiments." (PMID 38253555, 2024). "On one hand, the pivotal role of NLRP7 in inflammation and cancer immunity, as well as association with tumor metastasis is revealed; on the other, L1CAM was reported to get involved in tumor invasiveness across a number of malignancies except for LUAD metastases which remains controversial." (PMID 39697539, 2024). "Moreover, upregulation of CLU expression combined with L1CAM mediated signalling, a marker of tumour cells with metastatic potential, within LS174T CRC tumour cells results in substantial metastasis formation within the liver and spleen after transplantation." (PMID 38319453, 2024). "This L1CAM pathway leads to the activation of the constitutive nuclear factor NF-κB pathway by enhancing the IL1β expression, which further promotes cell motility, tumor cell growth, and cancer metastasis." (PMID 37893107, 2023).
tumor (continued). "Notably, in order to resist the intracranial colonisation of invading tumour cells, brain‐resident astrocytes attempt to block the L1CAM‐mediated vascular co‐option by releasing plasminogen activator (PA), which can cleave and inactivate L1CAM." (PMID 37830128, 2023). "Other integrin-mediated tumor cell adhesion includes αVβ1 or αVβ3 on tumor cells with L1 cell adhesion molecular (L1CAM) on the endothelium and α4β1 on tumor cells with vascular cell adhesion molecule-1 (VCAM1) on the endothelium, further allowing CTCs to extravasate and form distant metastases." (PMID 37046617, 2023). "The control group exhibited adherent clonal growth and a highly pro-angiogenic phenotype, indicating that the L1CAM may mediated perivascular tumor niche promotes metastasis." (PMID 37015905, 2023). "Recent studies have shown that L1CAM plays a crucial role in tumor progression." (PMID 37015905, 2023). "The most significant contribution of L1CAM expression in tumor development may occur during the early stage of EMT, when cancer cells gain motility and invasive properties." (PMID 37200263, 2023). "L1CAM expression is related to tumor cells with enhanced motility." (PMID 37298731, 2023). "(ii) L1CAM is recognized as a tumor antigen involved in motility." (PMID 37286800, 2023). "ssGSEA analysis showed that L1CAM positively connected with cellular response to hypoxia, tumor proliferation signature, DNA repair, G2M checkpoint, MYC targets, TGFB, IL-10 anti-inflammatory signaling pathway, DNA replication, collagen production, and ECM degradation." (PMID 36212450, 2022). "Furthermore, recent reports have indicated that L1CAM plays an important role in the severity and invasion of the metastatic tumor by facilitating vascular co-option, promoting migration, outgrowth and colonization of tumor cells in the brain parenchyma." (PMID 35525225, 2022). "In addition, L1CAM depletion lowered the viability of etoposide‐resistant RB cells for this chemotherapeutic drug and significantly decreased their tumor growth in vivo." (PMID 34228897, 2022). "Moreover, L1CAM depletion decreased viability and tumor growth of etoposide‐resistant RB cell lines upon etoposide treatment in vitro and in vivo." (PMID 34228897, 2022). "The results presented indicate that L1CAM may play an important role in RB progression and has an impact on viability and in vivo tumor growth of highly aggressive etoposide‐resistant RB cells." (PMID 34228897, 2022). "To investigate whether L1CAM influences RB cells' tumor growth, we used the CAM assay as in vivo model." (PMID 34228897, 2022). "Furthermore, the extracellular domain of the L1CAM can be a regulatory membrane proximally cleaved from the tumor cell surface or tumor cell–derived vesicles by several proteases such as the disintegrin and metalloprotease (ADAM) family." (PMID 36387224, 2022). "In addition, previous studies have also indicated the involvement of L1CAM in the tumor cell invasion, metastasis, and chemoresistance." (PMID 35525225, 2022). "Additionally, L1CAM silencing also suppressed the pro-tumor effects induced due to TPH1 overexpression." (PMID 35473609, 2022). "Considering the NSMP group, it may be stratified based on histological (i.e., tumor grade and histotype, LVSI, and depth of myometrial invasion), immunohistochemical (i.e., L1CAM expression), or molecular (i.e., CTNNB1 mutation) features." (PMID 35463299, 2022). "In the search for additional biomarkers useful for further NSMP prognostic stratification, we found that L1CAM expression was significantly associated with a poor outcome, regardless of tumor grade and FIGO stage." (PMID 36358847, 2022). "Forty nine (53%) tumours were classified as L1CAM positive, similar to the 47% positive cases in the Italian cohort and significantly associated with non‐endometrioid histology, high‐grade, advanced age and reduced response to platinum‐based chemotherapy treatment." (PMID 35429348, 2022).